SLC25A40 (solute carrier family 25 member 40)
Description:
Probable mitochondrial transporter required for glutathione import into mitochondria. Glutathione, which plays key roles in oxidative metabolism, is produced exclusively in the cytosol and is imported in many organelles. Mitochondrial glutathione is required for the activity and stability of proteins containing iron-sulfur clusters, as well as erythropoiesis (By similarity).
Synonyms: MCFP
Tractability: Antibody: UniProt predicts a signal peptide or a membrane-spanning region. PROTAC: ubiquitination databases record sites on it; its protein half-life has been measured.
Gene: Protein-coding gene on chromosome 7 (87,833,561 to 87,876,404, reverse strand). Ensembl gene ENSG00000075303.
Subcellular location: Mitochondrion inner membrane
Gene Ontology:
Molecular function: glutathione transmembrane transporter activity; protein binding
Biological process: erythrocyte development; glutathione transmembrane transport; mitochondrial transmembrane transport; transmembrane transport
Cellular component: mitochondrion; mitochondrial inner membrane
Genetic constraint (gnomAD): Loss-of-function variants: 15 observed, 18.79 expected, observed/expected ratio (o/e) 0.8, 90% interval 0.53 to 1.23. The upper end of that interval is the gene's LOEUF score, 1.23, which puts it in group 5 of 6, group 1 being the genes least tolerant of losing a copy. Missense variants: 147 observed, 169.03 expected, observed/expected ratio (o/e) 0.87, 90% interval 0.76 to 1. Synonymous variants: 47 observed, 56.22 expected, observed/expected ratio (o/e) 0.84, 90% interval 0.66 to 1.07.
Homologues: Orthologues: chimpanzee SLC25A40 (99% identical), macaque SLC25A40 (98% identical), dog SLC25A40 (91% identical), rabbit SLC25A40 (90% identical), pig SLC25A40 (89% identical), mouse Slc25a40 (83% identical), guinea pig SLC25A40 (82% identical), rat Slc25a40 (75% identical), tropical clawed frog slc25a40 (63% identical). Paralogues in human: SLC25A39 (51% identical), SLC25A12 (26% identical), SLC25A13 (26% identical), SLC25A18 (23% identical), SLC25A14 (23% identical), SLC25A22 (23% identical), SLC25A21 (23% identical), SLC25A25 (22% identical), SLC25A30 (22% identical), SLC25A28 (22% identical), SLC25A1 (22% identical), SLC25A20 (22% identical), and 37 more.
Diseases named in the same sentence as SLC25A40 in open-access papers:
SLC25A40 is named in the same sentence as 9 diseases in open-access papers, as found by Europe PMC text mining. Sharing a sentence is not in itself a finding about the gene and the disease. The quoted sentences say what the papers report.
hypertriglyceridemia (3 papers, 2019 to 2024). A laboratory test result indicating elevated triglyceride concentration in the blood. "A population study suggested that the SLC25A40 variant may be associated with hypertriglyceridemia, as whole-gene testing confirmed the link between triglyceride levels and rare, highly conserved coding variants of SLC25A40." (PMID 39850557, 2024).
ovarian carcinoma (2 papers, 2016 to 2020). A malignant neoplasm originating from the surface ovarian epithelium. "We performed targeted sequencing of a 500 kb region of chromosome 7 that contained both ABCB1 and SLC25A40, which is the most common translocation partner for ABCB1 in chemotherapy-treated breast and ovarian cancer patients." (PMID 33167906, 2020).
tumor (3 papers, 2013 to 2025). "SLC25A40 expression is much lower than SLC25A39 expression, which is increased in many tumor samples compared to the paired normal samples, while SLC25A40 changes are minimal." (PMID 39934670, 2025).
cancer (2 papers, 2025). A tumor composed of atypical neoplastic, often pleomorphic cells that invade other tissues. "For our application, classification models predict the known mGSH transporter SLC25A39 but not SLC25A40 as being highly probably related to mGSH metabolism in cancers." (PMID 39934670, 2025).
neurological disorders (1 paper, 2020). "The human SLC25A39 and SLC25A40 mitochondrial carriers could be involved in similar pathways in the brain, considering that they reside in risk loci for epilepsy and that the potentiation of glutamatergic transmission might predispose to neurological disorders." (PMID 32842667, 2020).
SLC25A40 also shares sentences with these, for which no sentence is quoted: breast carcinoma (2 papers); epilepsy (1); leukemia (1); mitochondrial disease (1).